XIAP-AS1 (XIAP antisense RNA 1)
Gene: Long non-coding RNA gene on chromosome X (123,872,626 to 123,873,932, reverse strand). Ensembl gene ENSG00000237331.
Diseases named in the same sentence as XIAP-AS1 in open-access papers:
XIAP-AS1 is named in the same sentence as 4 diseases in open-access papers, as found by Europe PMC text mining. Sharing a sentence is not in itself a finding about the gene and the disease. The quoted sentences say what the papers report.
gastric cancer (1 paper, 2017). A primary or metastatic malignant neoplasm involving the stomach. "However, XIAP-AS1 up-regulation inhibited the apoptosis induced by TRAIL, which further showed XIAP-AS1 involvement in the resistance of gastric cancer cells to TRAIL." (PMID 28792527, 2017). "Subsequently, we probed the location of XIAP-AS1 in gastric cancer cells using RNA FISH and determined that XIAP-AS1 was mostly distributed in the nucleus." (PMID 28792527, 2017).
gastric tumor (1 paper, 2017). "Furthermore, XIAP-AS1 knockdown promotes TRAIL-induced apoptosis in gastric tumor cells, suggesting XIAP-AS1 as a potential therapeutic target for regulating TRAIL-induced cell death in gastric tumor cells." (PMID 28792527, 2017).
stomach adenocarcinoma (1 paper, 2017). "Also, the levels of XIAP-AS1 in stomach adenocarcinoma (n = 285) and normal tissues (n = 33) derived from TCGA were analyzed and the results showed that XIAP-AS1 was highly expressed in stomach adenocarcinoma." (PMID 28792527, 2017).
tumor (1 paper, 2017). "Moreover, in an in vivo mouse xenograft model, tumor cell proliferation was inhibited by XIAP-AS1 knockdown in response to TRAIL administration." (PMID 28792527, 2017).